NLRP3 (NLR family pyrin domain containing 3)
Diseases named in the same sentence as NLRP3 in open-access papers (continued):
Sharing a sentence is not in itself a finding about the gene and the disease.
pulmonary fibrosis (continued). "In view of the recognized importance of the NLRP3 pathway in particle-induced diseases, such as MWCNT-induced lung fibrosis, we propose to use our approach as an early in vitro screening tool when assessing the hazard of particles, fibers, and MNPs in a hierarchical testing strategy." (PMID 36008988, 2022). "Furthermore, our findings demonstrated that NecroX-5 ameliorated BLM-induced pulmonary fibrosis by inhibiting the TGF-β1/Smad2/3-mediated EMT process, which is dependent on the inhibition of NLRP3 inflammasomes." (PMID 35596212, 2022). "Similarly, in the BLM-induced pulmonary fibrosis model mice, TA293 suppressed the expression of NLRP3, but mitoTA293 increased these effects." (PMID 34573030, 2021). "The studies have found that NLRP3 inflammasome transforms ECs into EMT, forming pulmonary fibrosis." (PMID 34177893, 2021). "Meanwhile, epithelial-mesenchymal transition (EMT) in pulmonary fibrosis may also be related to activating the NOD-like receptor protein (NLRP) 1 and NLRP3 inflammatory pathways." (PMID 34394391, 2021). "While the study of the NLRP3 inflammasome has been explored in various lung fibrosis models, the role of AIM2 inflammasome has not been fully investigated." (PMID 32121297, 2020). "Moreover, protein levels of ERK/NF-κB/NLRP3 and collagen were increased, but the protein level of Spry1 was decreased in BLM-induced pulmonary fibrosis." (PMID 29084974, 2017). "Without NLRP3 inflammasome signaling, bone marrow chimeric mice lacking vimentin have decreased lung fibrosis when induced by asbestosis." (PMID 29029603, 2017). "Indeed, several studies using KO mice for several components of inflammasome pathway including NLRP3, ASC and caspase-1 showed a reduction of experimental pulmonary fibrosis induced by bleomycin in mice." (PMID 27247426, 2016). "These authors also found that BLM-induced enhancement of lung collagen production was attenuated in mice lacking either NLRP3 or caspase-1, and that NLRP3– and ASC–deficient mice were resistant to BLM-induced skin and lung fibrosis." (PMID 26497260, 2015). "However, significant data linking luteolin’s effects on NLRP3 to modulate lung fibrosis is currently lacking, indicating the need for further research." (PMID 39966334, 2025). "In the context of altering the lung tissue expression of NF-κB and the inflammasome NLRP3, the results of the present work regarding the induced (BLM) group and the VCN-treated group were supported by a recently published study on the ameliorating effect of vincamine in pulmonary fibrosis in mice." (PMID 38750140, 2024). "Notably, a direct interaction between vimentin and NLRP3 was demonstrated as well as an important role for macrophages based upon the finding that bone marrow chimeric mice lacking vimentin have decreased lung fibrosis as well as levels of caspase-1 and IL-1β." (PMID 26370974, 2015). "Moreover, it was demonstrated that NLRP3 and ASC deficient mice did not develop pulmonary fibrosis after bleomycin exposure whereas wild type mice had increased collagen deposition the lungs." (PMID 24915862, 2014). "In conclusion, the current study indicates that the exosomes derived from MenSCs could ameliorate pulmonary fibrosis by transporting miRNA Let-7 into the alveolar epithelial cell, which subsequently downregulated ROS levels, LOX1 expression, mtDNA damage, and inflammatory body NLRP3 activation." (PMID 31949877, 2019). "The absence of NLRP3 and IL-18 in P2RX7-expressing immune cells abrogated the ability of HEI3090 to inhibit lung fibrosis because the lung architecture and collagen fibers intensity resembled that of control mice." (PMID 38300690, 2024). "Previous studies have shown that NLRP3 modulates EMT in bleomycin-induced lung fibrosis, and although NLRP3 contributes to the regulation of EMT in lung fibrosis, no studies have investigated its effects in a lung fibrosis model induced by high-dose local irradiation." (PMID 38003456, 2023).
pulmonary fibrosis (continued). "Furthermore, we also indicated that cAMP/PKA may act as a negative feedback regulator of ER stress-induced NLRP3 inflammasome activation, thereby inhibiting type II AEC pyroptosis and eventually alleviating pulmonary fibrosis." (PMID 36033388, 2022).
periodontitis (145 papers, 2014 to 2026). An acute or chronic inflammatory process that affects the tissues that surround and support the teeth. "There is a strong correlation between NLRP3-dependent inflammatory signaling and periodontitis- bone loss." (PMID 41596738, 2026). "NLRP3 inflammasome activation is associated with M1/M2 macrophage imbalance, which is a driver of a number of inflammatory diseases including periodontitis." (PMID 40861497, 2025). "Another study reported that the TRPM2–Ca2+–NLRP3 axis has been implicated in lupus nephritis and periodontitis-associated bone defects as a common regulatory node for inflammatory–osteogenic imbalance." (PMID 41293090, 2025). "NLRP3 influences alveolar bone loss in ligature-induced periodontitis via osteoclast differentiation." (PMID 38945951, 2024). "The severity of periodontitis caused by OMVs is close to the effect of F. nucleatum itself, due to the activations of NLRP3 inflammasomes, inflammatory factors, and extracellular degradation." (PMID 39475060, 2024). "In a ligature-induced periodontitis model, compared with wild-type mice,NLRP3-knockout mice exhibited decreased loss of alveolar bone, reduced release of IL-1β and impaired differentiation of osteoclasts." (PMID 38596842, 2024). "Inhibition of NLRP3 inflammasome formation holds the potential to limit alveolar bone loss due to periodontitis." (PMID 38385066, 2024). "O-GlcNAcylation of NLRP3 enhances HGF-induced pyroptosis caused by LPS in the context of periodontitis." (PMID 39742284, 2024). "Studies have shown that a variety of pathogens associated with periodontitis can cause NLRP3 inflammasome activation and inflammatory responses." (PMID 38596842, 2024). "NLRP3, a key component of the innate immune system, has been implicated in the inflammatory processes underlying both periodontitis and ACS." (PMID 38451305, 2024). "The current study, to the authors' knowledge, is the first study to investigate the relationship between genetic variation of NLRP3 and periodontitis risk in an Iraqi Arab population." (PMID 36812929, 2023). "Clinical attachment loss and NLRP3 rs10925024 additionally demonstrated a significant positive correlation in the periodontitis subjects." (PMID 36812929, 2023). "The suppression of the NLRP3 inflammasome enables alleviation of periodontitis in a mouse model; meanwhile, NLRP3 knockout reduces periodontal bone loss during P. gingivalis infection in mice." (PMID 34992737, 2022). "NLRP3 inflammasome contribution to alveolar bone loss in periodontitis has been studied in other experimental systems using various KO NLRP3 mice on C57Bl/6 genetic background." (PMID 35281020, 2022). "As one of the most important inflammasomes and one of the early biomarkers of periodontitis, the activation of NLRP3 inflammasome is associated with the facilitated cardiac fibroblasts and the AF development." (PMID 35692374, 2022). "Study has indicated that multiple pathogens associated with periodontitis can cause NLRP3 inflammasome activation and apoptosis of osteoblast." (PMID 36185327, 2022). "Several studies have indicated that NLRP3 inflammasome production is a feature of periodontitis and reflected by increased levels of NLRP3-associated proteins in serum and saliva." (PMID 35844512, 2022). "The activation of nucleotide‐binding leucine‐rich repeat protein 3 (NLRP3) inflammasome in inflammation-induced alveolar bone loss has emerged as an important mechanism in the pathogenesis of periodontitis." (PMID 35281020, 2022). "P. gingivalis induced the activation of pyroptosis-related NLRP3 inflammasome, which is also implicated in atherosclerosis associated with periodontitis." (PMID 35844512, 2022). "The initiation and activation of NLRP3 starts with the oral microbiome and its association with the pathogenesis and progression of several oral diseases, including periodontitis, periapical periodontitis, and oral squamous cell carcinoma (OSCC)." (PMID 35052653, 2022).
periodontitis (continued). "Recently, more attention has been paid to the association between NLRP3 inflammasome and periodontitis." (PMID 33382502, 2021). "MCC950, a specific inhibitor of the NLRP3 inflammasome, inhibits osteoclast differentiation, thereby reduces alveolar bone loss in periodontitis." (PMID 33382502, 2021). "In a mouse periodontitis model, knock out of NLRP3 decreases Porphyromonas gingivalis‐associated alveolar bone loss." (PMID 33382502, 2021). "Knockout of the Nlrp3 gene or treatment with an NLRP3 inhibitor significantly reduces the number and differentiation of osteoclasts, thereby decreasing alveolar bone loss in mice with ligature-induced periodontitis." (PMID 34177950, 2021). "Longitudinal studies are required to investigate the function of NLRP3 (rs4612666) and IL-1β (+3954) gene polymorphisms as therapeutic markers for periodontitis and coronary heart disease." (PMID 34501201, 2021). "Our findings reveal that NLRP3 regulates alveolar bone loss in ligature‐induced periodontitis by promoting osteoclastic differentiation." (PMID 33382502, 2021). "A recent study also showed a stronger association of the extent of periodontitis with an allele frequency of NLRP3 (rs4612666) between periodontitis subjects and healthy controls." (PMID 34199122, 2021). "Some authors have suggested a close relationship between Nek7 and NLRP3 pathway activation and pyroptotic cell death in the onset and development of diabetes-associated periodontitis, and that metformin ameliorates the pyroptosis outcome." (PMID 34572060, 2021). "The aim of the study was to evaluate the polymorphisms in NLRP3 inflammasome, cytokine and receptor of cytokines genes in the development of periodontitis." (PMID 31978095, 2020). "This study investigates the role of NLRP3 inflammasome and its main effector Caspase-1 in inflammation and alveolar bone resorption associated with periodontitis." (PMID 32385413, 2020). "The results obtained showed the distribution of two polymorphisms of NLRP2 (rs17699678 C>T) and NLRP3 (rs35829419 C>A) genes in Polish subjects with pancreatic diseases and periodontitis." (PMID 26253076, 2015). "Correspondingly, compared with wild-type controls, NLRP3- or caspase-1–deficient mice exhibit significantly less alveolar bone loss in ligature-induced periodontitis models, underscoring the crucial role of inflammasome signaling in periodontal bone resorption." (PMID 41596738, 2026). "Clinical studies have consistently demonstrated elevated levels of NLRP3, caspase-1, IL-1β, and IL-18 in the gingival tissues and gingival crevicular fluid of patients with periodontitis, correlating with attachment loss, probing depth, and bleeding on probing." (PMID 41596738, 2026). "Furthermore, NLRP3 activation status has emerged as a potential biomarker for cardiovascular risk stratification in patients with periodontitis." (PMID 40869031, 2025). "Additionally, critical inflammatory mediators associated with periodontitis, such as iNOS, NLRP3, TNF‐α, and IL‐1β, were significantly modulated." (PMID 41020683, 2025). "Similarly, dapansutrile, via selective NLRP3 inflammasome inhibition, demonstrates potential in mitigating periodontitis-related bone loss." (PMID 41415576, 2025). "A well-studied gram-negative subgingival organism thought to be involved in driving periodontitis, P. gingivalis, was shown to induce gene expression of IL-1β and IL-18 cytokines in gingival tissues and through NLRP3 inflammasome activation to induce alveolar bone loss in mice." (PMID 38817019, 2024). "The present study concluded that NLRP3 SNP may have a role in periodontitis genetic susceptibility in the population." (PMID 36812929, 2023). "In the present investigation, NLRP3 polymorphisms were discovered that may indicate higher genetic susceptibility to periodontitis." (PMID 36812929, 2023).
periodontitis (continued). "The NLRP3 inflammasome, which is responsible for IL-1β secretion, significantly contributes to alveolar bone resorption by promoting osteoclast differentiation, and NLRP3 knockout reduced pathological alveolar bone loss in experimental periodontitis." (PMID 36782172, 2023). "While there was a slightly higher frequency of TC + CC genotypes of NLRP3 at rs4612666 in periodontitis which accounts for 93.5 versus 90.6% in healthy controls and is associated with an increased likelihood of having periodontitis compared with those with the TT genotype (OR = 1.500) times." (PMID 36812929, 2023). "In summary, MCC950 may serve as a promising new treatment alternative for periodontitis by blocking NLRP3 inflammation and rescuing alveolar bone loss." (PMID 36185327, 2022). "Furthermore, as several biomarkers (e.g. TGF-β1, transglutaminase 2, NLRP3) have been implicated in the pathogenesis of periodontitis, it would be of interest to evaluate the effects of the test oral rinse on these early biomarkers." (PMID 36324127, 2022). "In summary, by using ligature‐induced periodontitis murine models, we have demonstrated that both NLRP3 deficiency and MCC950 reduce the number of osteoclast precursors and prevent osteoclast differentiation, thereby protect against alveolar bone loss in ligature‐induced periodontitis." (PMID 33382502, 2021). "NLRP3 inflammasome has been reported to be associated with periodontitis closely." (PMID 33382502, 2021). "Hence, the identification of important genetic polymorphisms such as NLRP3 (rs4612666) and IL-1β (+3954) will pave the way for the development of point of care treatment for patients suffering from periodontitis and coronary heart disease." (PMID 34501201, 2021). "It has been reported that P. gingivalis-LPS could activate NLRP3 inflammasome in mouse periodontal ligament fibroblasts and cause chronic periodontitis; however, the relevance of NLRP3 inflammasome activation and MSC function is far from clear." (PMID 32059742, 2020). "In addition, our study helped in understanding the relationship between man and periodontitis by demonstrating that polymorphisms in NLRP3 and cytokine genes are associated with the risk of developing PD." (PMID 31978095, 2020). "Similarly, there is a distinct correlation between periodontitis and rs35829419 C>A in NLRP3 polymorphism." (PMID 26253076, 2015). "Notably, periodontitis-associated bacteria may stimulate NLRP3 and enhance the progression and development of tumors in an in situ oral squamous cell carcinoma (OSCC) model in mice." (PMID 38904007, 2024). "The aim of this study was to determine whether periodontitis in Arab populations from Iraq is correlated with NLRP3 gene polymorphisms and measure clinical periodontal parameters and investigate their association with genetic polymorphisms of the NLRP3." (PMID 36812929, 2023). "However, Nod2 knockout was shown to decrease osteoclastogenesis and alveolar bone destruction in mouse periodontitis induced by heat-killed A. actinomycetemcomitans, which may be associated with the affected NLRP3 inflammasome activity." (PMID 34177950, 2021). "Therefore, we intend to investigate whether NLRP3 can regulate periodontitis‐related alveolar bone loss by affecting osteoclast differentiation." (PMID 33382502, 2021). "Thus, NLRP3 inflammasome contribute significantly to the pathologic bone loss in periodontitis." (PMID 33382502, 2021). "In a rat model of periodontitis, EGCG reduced bone loss by downregulating NLRP3 and NF-κB expression in periodontal tissues, whereas curcumin improved PDL integrity by upregulating the anti-inflammatory cytokine IL-10 and suppressing IL-1β and IL-6 expression." (PMID 41596738, 2026). "Although NLRP3 and inflammatory cytokine levels increased in periodontitis, they were effectively reduced after CTSB inhibition in the periodontal region." (PMID 41869360, 2026).